DKK3 (dickkopf Wnt signaling pathway inhibitor 3)
Diseases named in the same sentence as DKK3 in open-access papers (continued):
Sharing a sentence is not in itself a finding about the gene and the disease.
tumor (continued). "Thus, DKK-3 could contribute to limiting immune cell infiltration in the tumor microenvironment." (PMID 38201279, 2023). "Dickkopf-related protein 3 (Dkk3), as a member of the Dickkopf WNT signaling pathway inhibitor family, has a tumor suppressive effect." (PMID 36230547, 2022). "On the other hand, deletion and/or neutralization of Dkk3 in TCR/MHC class-I double transgenic mice increases local CD8+ T cell infiltration and enhances MHC class-I mismatched anti-tumor and skin graft rejection." (PMID 36497305, 2022). "Dickkopf Wnt signaling pathway inhibitor 3 (DKK3), localized on 11p15, is a potential tumor suppressor gene for the often deleted-locus in cancerous cells." (PMID 35924156, 2022). "Dkk-3 was found to enhance PDAC metastasis and interfere with chemotherapy resistance, while a combination of a Dkk-3 function blocking antibody, JM6-6-1, and immune checkpoint inhibitors was found to limit tumor growth and survival." (PMID 36497305, 2022). "Overexpression of another Wnt antagonist, Dickkopf-3 (DKK-3), also retarded tumor growth and pulmonary metastasis in xenograft model." (PMID 34130697, 2021). "Inhibition of these PAIPs in G-415 cell line largely supports the role of DKK3 in regulation of PP2A and its combined role in tumor suppression is further warranted." (PMID 33670899, 2021). "Combined with the increase in DKK3 and MMP3 expression seen in tumor tissue, the demonstration of aberrant activation of LEF1 in the current study adds OSA to the range of cancers that exhibit aberrant Wnt activity." (PMID 32854182, 2020). "It has been reported that Dkk3 might orchestrate concomitant activation of β-catenin and YAP/TAZ in cancer-associated fibroblasts (CAFs) by interfering with the Kremen negative regulator and increasing cell-surface levels of LRP6 as an HSF1 effector, required to promote tumor aggressiveness." (PMID 33425757, 2020). "DKK3, found to be increased at the gene and protein level in FCA, is considered to be a tumor suppressor involved in several cancers and, most interestingly, described as required for maintaining the integrity of secretory vesicles in mouse adrenal glands." (PMID 33066652, 2020). "DKK3, in contrast to other members of the Dickkopf family, does not interfere with the WNT signaling pathway and is proposed to be a tumor suppressor gene." (PMID 32759649, 2020). "Therefore, DKK3 may be a therapeutic target that may help tumor cells recover sensitivity to DTX." (PMID 32850327, 2020). "MT1-MMP regulated the transcription of dickkopf-related protein 3 (DKK3) in urothelial cells and Smad1 in several tumor cell lines." (PMID 31137480, 2019). "Stromal DKK3 expression in human tumours positively correlated with the expression of CAF markers ACTA2, FAP and COL1A2, supporting a link between DKK3 and CAFs." (PMID 30631061, 2019). "Three genes, AXIN2, DKK3, and SFRP1, which are known as tumor suppressors in a broad range of human malignancies including NSCLC, are targeted by miR-582-3p and suppress their protein levels." (PMID 30621620, 2019). "To determine whether reduced DKK3 expression correlated with disease presentation and/or outcome, we analyzed statistical correlation to various patient characteristics, including age, gender, tumor size, tumor weight, ENSAT stage, and hormone secretion phenotypes." (PMID 28249601, 2017). "Remarkably, Dkk-3 is able to up-regulate ATF3 and enhance Smad3 phosphorylation in tumor cell lines." (PMID 28352232, 2017). "Altogether, our results show that both MSCs and tumor cells respond to irradiation by enhancing the expression of the proteins TRAIL and DKK3 as well as of the TRAIL receptor DR5." (PMID 26378036, 2015). "AXIN2, DKK3 and SFRP1 have been identified as negative regulators of Wnt signalling and suggested to be tumour suppressors in a broad range of human malignancies including NSCLC14." (PMID 26468775, 2015).
tumor (continued). "We also observed that after irradiation of the tumor cells with 6 Gy TRAIL, DR5and DKK3 were up-regulated in A375 and we observed the up-regulation of DR5 in G361." (PMID 26378036, 2015). "Overall, our results demonstrate that miR-582-3p activates Wnt signalling by targeting AXIN2, DKK3 and SFRP1; enhances stem cell-like traits; and leads to tumour recurrence and poor prognosis in NSCLC patients." (PMID 26468775, 2015). "Since the REIC/Dkk-3 protein differentiates CD14+ monocytes into the DC phenotype, the REIC/Dkk-3 protein overexpressed and secreted by Ad-REIC transfection at the tumor site differentiates and activates DCs." (PMID 24527065, 2014). "Transcription of dickkopf-related protein 3 (DKK3) in urothelial cells and Smad1 in several tumor cell lines was regulated by MT1-MMP." (PMID 24549119, 2014). "Based on elevated Dkk-3 expression in BPH and PCa-reactive stroma 1, the influence of Dkk-3 on remodeling of the tumor adjacent stroma was analyzed in vitro." (PMID 23765731, 2013). "Our findings demonstrated that DKK3 regulated Wnt/β-catenin and JNK signalling, thus acting as a tumour suppressor." (PMID 23890219, 2013). "The suppression of DKK1 expression has been observed in several tumors, and although elevated level of the DKK family occur in a number of tumor cells, most reports to date have been concerned with DKK1 and DKK3." (PMID 19247449, 2009). "While the upregulation of DKK3 and ALDOC enhanced differentiation, the downregulation of ID1 may reduce the oncogenic potential, reinforcing the tumor-suppressive effects of the treatment." (PMID 40753072, 2025). "Additionally, it has been demonstrated that Dickkopf-3 (Dkk3, a heat shock factor 1 effector)-driven β-catenin and the YAP/TAZ signaling pathway can activate CAFs that behave aggressively in promoting tumor phenotypes." (PMID 40805183, 2025). "Neuron functional genes such as CaMK2N1, MEG3, SNCB, SYT1, DKK3 are almost expressed in the marginal area of the tumor (not shown)." (PMID 39257581, 2024). "Subsequent analysis of tumor cells after expansion ex vivo confirmed that nonrejected shDKK3 tumors regained DKK3 expression — likely explaining the persistence of these tumors." (PMID 37847565, 2023). "In our hands, DKK3 did not directly affect tumor cell proliferation, but instead showed tumor-promoting effects when in contact with the immune system." (PMID 37847565, 2023). "In particular, DKK3 and PDPN were both increased markedly on tumor-proximal cells." (PMID 37350578, 2023). "Similar studies confirmed that activating the p38MAPK pathway by osteoblast-secreted factors, such as BMP1, dickkopf-related protein 3 (DKK3), vasorin, and neogenin, might drive tumour cells to a dormant state." (PMID 36307871, 2022). "The results presented in the current study thus appear to contradict these earlier findings, with both MMP3 and DKK3 expressed more highly in tumor compared to non-tumor tissue." (PMID 32854182, 2020). "Unlike other members of DKK family, role of DKK3 in Wnt signaling is still elusive however it is reported to have both oncogenic and tumor suppressive property." (PMID 31737564, 2019). "To test whether DKK3 plays a tumor suppressor role in ACC in vitro, we investigated the expression pattern and regulation of DKK3 in two ACC cell lines, SW-13 and NCI-H295R." (PMID 28249601, 2017). "Although DKK3−/− MSCs were normally persistent within the tumor transplants, they did not accelerate tumor growth in C57BL/6 mice as WT MSCs did." (PMID 26734010, 2015). "Growth of these tumor cells in C57BL/6 mice was significantly accelerated when tumor cells were injected together with WT MSCs in comparison to tumors inoculated without any MSCs or with DKK3−/− MSCs (both p < 0.0001)." (PMID 26734010, 2015).
tumor (continued). "To investigate whether DKK3 produced by MSCs could also limit the growth of a strongly antigenic tumor, we used the RMA-mOVA tumor cell line." (PMID 26734010, 2015). "In addition, at the Ad-REIC-treated tumor site, secreted REIC/Dkk-3 protein plays a cytokine-like role in inducing monocyte differentiation to a specific DC phenotype and appear to be involved in systemic anticancer immunity." (PMID 24527065, 2014). "Therefore, intratumoral Ad-REIC treatment activates the DCs via the actions of secreted REIC/Dkk-3 proteins and TAAs released at the Ad-REIC-injected tumor sites." (PMID 24527065, 2014). "Dickkopf 3 (Dkk3) is well established as a tumor suppressor in several tumor types, but not much is known about the regulation of its expression." (PMID 25029272, 2014). "DKK3 down-regulated stem markers such as NANOG, ABCG2 and OCT4, thus may reverse the stem cell-like phenotype of tumour cells." (PMID 23890219, 2013). "In addition, only DKK3 and ITIH5 methylation showed a significant concordance in tumor tissue and paired serum specimens." (PMID 23320751, 2013). "Dkk-3-transfected and vector control-transfected 143B cells (equally resuspended in 0.03 mL of PBS to obtain 1 × 107 cells/mL PBS) were injected percutaneously into the tibia of anesthetized nude mice and tumor size was measured every 3 days." (PMID 23476112, 2013). "Tumor samples from 155 patients with stages IIIB to IV NSCLC who received EGFR-TKI therapy were analyzed for DNA methylation status of Wnt antagonist genes, including SFRP1, SFRP2, SFRP5, DKK3, WIF1, and APC, using methylation specific PCR (MSP) method." (PMID 23009178, 2012). "Estimated OS rates after 10 years were 54% for patients with DKK3-methylated tumors, in contrast to patients without DKK3 methylation in the tumor, who had a favorable 97% OS after 10 years (p < 0.001)." (PMID 19570204, 2009). "Most evidence suggest DKK3 exerts a tumour suppressive function by inhibiting a non-canonical Wnt signalling branch referred to as the planar cell polarity (PCP) pathway." (PMID 18826564, 2008). "More than half of the PDACs (54.8%; 51 of 93) showed negative DKK3 staining in the epithelium, 30.0% (27 of 93) had a weak signal, and only 16.1% (15 of 93) displayed a moderate to intense DKK3 expression, irrespective of the tumor grade." (PMID 41147409, 2026). "Notably, the early absence of DKK3 alters tumor biology and therapeutic responsiveness to STAT3 inhibition, highlighting its transition from a tumor suppressor to an oncogene." (PMID 41147409, 2026). "Given its reported oncogenic roles in other cancers. and our observation of stage‐ and compartment‐specific DKK3 expression during PDAC progression, we hypothesized a context‐dependent switch whereby DKK3 is tumor‐suppressive initially but becomes oncogenic at later stages." (PMID 41147409, 2026). "However, DKK3 identified in type 1 cells was reported as a Wnt signaling pathway inhibitor in the DEG analysis, suggesting an inhibitory mechanism against Wnt signaling activation within the tumor." (PMID 39483146, 2024). "Interestingly, DKK-3 has oncogenic effects on other cells, in the tumor microenvironment, i.e., in a non-autonomous manner." (PMID 38201279, 2023). "Our results suggest that in LGG, unlike in GBM, DKK3 may also act as a tumor suppressor gene to some extent in relation to Wnt/β-catenin signaling." (PMID 37149563, 2023). "Further analyses strongly suggested that both secreted DKK3 and non-secreted DKK3 could activate Akt signaling in discrete ways, and consequently exert tumor promoting effects." (PMID 36376957, 2022).
tumor (continued). "Combined with the similar suppressive effects of ApoG2 and DKK3 on CC, we thus not hard to conclude that DKK3 might be a downstream regulator participated in ApoG2 exerting its tumor suppressive effects in CC in vitro and in vivo." (PMID 35924156, 2022). "Importantly, MSCs secrete Dkk3, and tumors containing Dkk3−/− MSCs show increased CD8+ T cell invasion and reduced M2-type macrophage infiltration, suggesting MSC-derived Dkk3 maintains the immune-suppressive capacity of the tumor microenvironment." (PMID 36497305, 2022). "However, a recent study found that Dkk-3 CRD1 interacts with the ECM protein, transforming the growth factor beta-induced (TGFBI), a secreted protein that has pro-invasive features and has been classified as a tumor-promoting factor." (PMID 36497305, 2022). "We also discovered several genes from the Wnt pathway with hypermethylation in EBVaGCs relative to LDs/normal tissues, including DKK3 (P = 0.0022), SFRP1 (P = 0.0034), and SFRP2 (P = 0.0005), and these genes have been reported to be frequently methylated and to function as tumor suppressors in NPCs." (PMID 34493320, 2021). "Additionally, the lack of TLR-4 maintains claudin-5 and DKK-3 proapoptotic properties, resulting in the limitation of tumor expansion." (PMID 32354122, 2020). "However, it is not known if stromal Dkk-3 plays a protective or tumor-promoting role in prostate disease." (PMID 29858602, 2018). "On the other hand, although Dickkopf-related protein 3 (DKK3) is much known to function as a positive regulator of Wnt signaling and a tumor suppressor through inducing apoptosis, none is known about its speculative effect in preterm birth." (PMID 28700733, 2017). "Silencing of DKK3 in SW13, a human ACC cell line with intact and inductile WNT signaling and endogenously expresses DKK3, did not affect growth or viability of cells but resulted in reduced clonogenic growth and increased motility, consistent with a tumor suppressor role for DKK3." (PMID 28249601, 2017). "DKK3 and DKK4 could be referred as the putative tumor suppressors." (PMID 27457487, 2016). "This indicated that the DKK3 produced by MSCs, but neither by the tumor cells nor by the environment, might be capable of down-modulating the immune response against this transplanted tumor." (PMID 26734010, 2015). "Presently, we cannot judge whether or not DKK3 can directly modulate the growth of the used tumor transplants in vivo." (PMID 26734010, 2015). "As for TWIST1, DKK3 might be useful as a cancer marker, but could not predict tumor progression, nor explain recurrence after hormonal therapy." (PMID 20976069, 2010). "Based on a mean OS of 141 months (95% CI: 127–154 months) patients without DKK3 methylation in the tumor tissue revealed much longer mean OS (170 months, 95% CI: 163–177 months) than patients with DKK3 methylation in the tumor tissue (113 months, 95% CI: 95–131 months)." (PMID 19570204, 2009). "No overexpression of Dkk-3 (NDDK-3 above 107%) was observed in ALL primary tumours." (PMID 15226763, 2004). "Therefore, we speculate if the reason why the role of DKK3 has not yet been established, unlike DKKs 1, 2, and 4, is because the role of DKK3 in Wnt/β-catenin signaling may change depending on the tumor grade or tumor type, as shown in our results." (PMID 37149563, 2023). "Upon DKK3 overexpression in 3 GBC cell lines, OCUG-1, NOZ, G-415, we observed the ability of these cell lines to form colonies was decreased significantly (p < 0.0001), suggesting DKK3 inhibits the capacity of single cells to proliferate and could act as potential tumor suppressor in GBC." (PMID 31737564, 2019). "In contrast, DKK3 was more highly expressed in human OSA cells overexpressing NKD2 and in tumor tissue, and also in tumor tissue compared to non-affected bone in naturally occurring canine OSA." (PMID 36570509, 2022).
tumor (continued). "Statistically, approximately 80% of the diagnosed tumours are non-muscle invasive bladder cancer (NMIBC) tissues, muscle invasive bladder cancer (MIBC) tissues exhibited significantly lower expression of DKK3." (PMID 32284738, 2020). "Among various differentially expressed WNT regulators, the expression of DKK3, a negative WNT regulator and a putative tumor suppressor in a wide variety of tumors, was found significantly reduced in the majority (6/7) of the ACC samples tested." (PMID 28249601, 2017). "Based on a mean DFS of 99 months (95% CI: 90–107 months) patients without DKK3 methylation in the tumor revealed longer mean DFS (110 months, 95% CI: 99–122 months) than patients with DKK3 methylation in the tumor (86 months, 95% CI: 75–97 months)." (PMID 19570204, 2009).